HSPA1A (heat shock protein family A (Hsp70) member 1A)
Diseases named in the same sentence as HSPA1A in open-access papers (continued):
Sharing a sentence is not in itself a finding about the gene and the disease.
Arthritis (1 paper, 2020). Inflammation of a joint. "Recombinant human HSPA1A suppresses the production of pro-inflammatory cytokines in RA FLS by inhibition of NF-κB pathway and decreases collagen-induced arthritis in mice." (PMID 32887899, 2020).
atrial fibrillation (1 paper, 2023). A disorder characterized by an electrocardiographic finding of a supraventricular arrhythmia characterized by the replacement of consistent P waves by rapid oscillations or fibrillatory waves that vary in size, shape and timing and are accompanied by an irregular ventricular response. "These genes include heat shock proteins Hspa1a and Hspa1b which serve as chaperones for other proteins involved in cytoskeleton function and have been associated with atrial fibrillation and colorectal polyp formation." (PMID 37113661, 2023).
autoimmune disease (1 paper, 2024). A disorder resulting from loss of function or tissue destruction of an organ or multiple organs, arising from humoral or cellular immune responses of the individual to their own tissue constituents. "Four genes (BLK, HSPA1A, IL12A, NEU1) have been targeted for drug development in autoimmune diseases and other conditions." (PMID 38997544, 2024).
Azoospermia (1 paper, 2017). Absence of any measurable level of sperm,whereby spermatozoa cannot be observed even after centrifugation of the semen pellet. "Expression of heat shock protein hspa1a in PMC, SC as well as spermatogonia and its downregulation in case of azoospermia indicate the involvement of hspa1a in sperm development." (PMID 28253373, 2017).
B-cell lymphoma (1 paper, 2020). "We were also unable to detect a change in methylation of HSPA1A using data from other heat shock studies, including a new data set from a B-cell lymphoma cell line and a published miCLIP data set, although coverage was again low 4,17." (PMID 32313079, 2020).
Behçet's syndrome (1 paper, 2022). "A study of Behçet's syndrome found that the HSPA1A protein level of active patients' PBMCs was significantly lower than that of healthy controls." (PMID 35655486, 2022).
breast adenocarcinoma (1 paper, 2012). "Surface bound/expressed and total Hsp25 (mouse HspB1) and Hsp72 (HspA1A) on 4T1 murine breast adenocarcinoma tumors suggest that tumor development and metastatic spread favors cells that express high levels of mouse HspB1 on their plasma surface." (PMID 22452810, 2012).
Cerebral ischemia (1 paper, 2025). Restriction of arterial blood supply to the brain associated with insufficient oxygenation to support the metabolic requirements of the tissue. "In a cerebral ischemia model, induction of high HSPA1A expression reduced neutrophil infiltration, inhibited the expression of proinflammatory factors, and inhibited apoptosis and glial scar formation." (PMID 39924492, 2025).
chronic hepatitis C infection (1 paper, 2025). "Similarly, it was found that patients with nonalcoholic steatohepatitis and chronic hepatitis C infection manifested elevated HSPA1A levels, which increased with the expansion of hepatic inflammation." (PMID 40066224, 2025).
chronic obstructive pulmonary disease (1 paper, 2025). A chronic and progressive lung disorder characterized by the loss of elasticity of the bronchial tree and the air sacs, destruction of the air sacs wall, thickening of the bronchial wall, and mucous accumulation in the bronchial tree. "Upregulation of HSPA1A has been observed in a variety of diseases, including Type 2 diabetes, Alzheimer's disease, various cancers, chronic obstructive pulmonary disease, prostatitis, or urinary tract infection." (PMID 40066224, 2025).
Cirrhosis (1 paper, 2021). A chronic disorder of the liver in which liver tissue becomes scarred and is partially replaced by regenerative nodules and fibrotic tissue resulting in loss of liver function. "Patients with decompensated cirrhosis presented a more limited alteration in TLR signalling genes, including 6 of the 17 upregulated genes observed in compensated cirrhosis, SIGIRR, IRAK1, HSPA1A, TOLLIP and ELK1, as well as downregulation of IL-1B." (PMID 34774066, 2021).
clear cell carcinomas (1 paper, 2021). "By global mRNA microarray profiling in a total of 196 epithelial OC patients (161 serous, 15 endometrioid, 11 mucinous, and 9 clear cell carcinomas), we found four candidates—HSPA1A, CD99, RAB3A and POM121L9P, which associated with OS and poor clinicopathological features." (PMID 33686173, 2021).
coronary artery stenosis (1 paper, 2023). "The PCA revealed that the expression signatures of RMRP, MIAT, NTT and the expression profiles of MALAT1, HSPA1A, and NLRP3 moderately differed between the thallium stress test (+) CAG (–) and thallium stress test (+) CAG (+) groups regardless of significant coronary artery stenosis." (PMID 37238718, 2023).
cystic fibrosis (1 paper, 2014). Autosomal recessive disorder caused by pathogenic variants in the CFTR gene (cystic fibrosis transmembrane conductance regulator), which encodes a chloride and bicarbonate channel expressed in epithelial cells, and follow the diagnosis criteria. "Consistent with the findings observed in cystic fibrosis bronchial epithelial (CFBE) cells, F508del-expressing hBE cells also showed elevated HSF1-P and I-Hsp70 protein levels, as well as increased I-Hsp70 (HspA1A & A6), I-Hsp90, and I-Hsp40 mRNA levels, relative to that seen in WT-expressing hBEs." (PMID 25406061, 2014).
diabetic ketoacidosis (1 paper, 2022). The metabolic condition resulted from uncontrolled diabetes mellitus, in which the shift of acid-base status of the body toward the acid side because of loss of base or retention of acids other than carbonic acid is accompanied by the accumulation of ketone bodies in body tissues and fluids. "This agrees with prior associations between shorter TL and increased risk of type 1 diabetes, and between the protein product of HSPA1A (Hsp72) and diabetic ketoacidosis." (PMID 35530816, 2022).
epilepsy (1 paper, 2023). A brain disorder characterized by episodes of abnormally increased neuronal discharge resulting in transient episodes of sensory or motor neurological dysfunction, or psychic dysfunction. "Overexpression of the HSPA1A gene has been observed in children with cerebral malaria and patients with epilepsy." (PMID 37242305, 2023).
graft versus host disease (1 paper, 2024). An immune system disorder that occurs after allogeneic hematopoietic stem cell transplant and is a reaction of donor immune cells against host tissues. "HSPA1A is linked to CD24FC, a medication used to treat severe acute respiratory syndrome and graft-versus-host disease (GVHD)." (PMID 38997544, 2024).
HCMV infection (1 paper, 2024). "In particular, the HSPs DNAJB1 and HSPA1A were the host genes that were most positively correlated with viral RNA expression in P. Thus, here we identified putative pro- and anti-viral host factors of HCMV infection in moDCs." (PMID 38409141, 2024).
Hepatitis (1 paper, 2010). Inflammation of the liver. "GRB2 and HSPA1A and B genes directly act on angiogenesis, TAF11 is known to be involved in artery passage, and the E2F1 transcription factor is known to be an angiogenesis positive inducer in hepatitis and cancer." (PMID 20426824, 2010).
hepatoblastoma (1 paper, 2009). Hepatoblastoma (HB) is a malignant hepatic tumor and is the most common pediatric liver cancer. "Examples are genes encoding heat shock 70 kDa protein 1A (Hsp70/HspA1A) in HeLa cells, prion protein (PrP) in neurons and metallothionein 2A (MT2A) in hepatoblastoma cells." (PMID 19305496, 2009).
Hyperinsulinemia (1 paper, 2018). An increased concentration of insulin in the blood. "Furthermore, it appeared that HspA1A (Hsp72) may be induced in pregnancy and released from a storage site into the circulation in response to excessive glucose ingestion, potentially as a regulatory mechanism to prevent excessive insulin release and the development of hyperinsulinemia." (PMID 30336561, 2018).
inflammatory bowel disease (1 paper, 2019). A spectrum of small and large bowel inflammatory diseases of unknown etiology. "In the intestinal mucosa of patients with inflammatory bowel disease, HSPA1A/B overexpression was found to be associated with a balanced inflammatory response to damaging factors." (PMID 30923583, 2019).
influenza (1 paper, 2024). An acute viral infection of the respiratory tract, occurring in isolated cases, in epidemics, or in pandemics; it is caused by serologically different strains of viruses (influenzaviruses) designated A, B, and C, has a 3-day incubation period, and usually lasts for 3 to 10 days. "Expression of HSPA1A/B was pronounced in the newborn brain, adult reproductive tissues (breast and vagina), heart, aorta, and adipocytes (in addition to influenza-infected macrophages)." (PMID 38201301, 2024).
kidney stone (1 paper, 2025). "Concurrently, six protein ratio pairs were found to inhibit kidney stone occurrence: GGT1/MME protein level ratio, ACE2/MME protein level ratio, ITIH3/VCAM1 protein level ratio, GZMA/TNFRSF8 protein level ratio, CRADD/HSPA1A protein level ratio and GZMA/TNFRSF4 protein level ratio." (PMID 40673688, 2025).
non-small cell lung carcinoma (1 paper, 2017). A group of at least three distinct histological types of lung cancer, including non-small cell squamous cell carcinoma, adenocarcinoma, and large cell carcinoma. "Regarding HSPA1A-based vaccines, a clinical trial was conducted to address the effect of a specific peptide corresponding to a region of HSPA1A, which activates NK cells in refractory metastatic colon cancer and non-small cell lung cancer patients." (PMID 28468249, 2017).
preeclampsia (1 paper, 2018). Preeclampsia is a hypertensive disorder of pregnancy that is characterized by new-onset hypertension with proteinuria presenting after 20 weeks of gestation, and depending on mild or severe forms may initially present with severe headache, visual disturbances, and hyperreflexia. "Potential involvement of stress-induced HSPA1A in adverse pregnancy outcomes, including preeclampsia and PTB, has previously been suggested." (PMID 30001343, 2018).
prostatic atrophy (1 paper, 2025). "In vivo, testosterone‐induced BPH (T‐BPH) rat models treated with the HSPA1A antagonist KNK437 exhibited prostatic atrophy and molecular changes consistent with reduced HSPA1A activity." (PMID 40066224, 2025).
respiratory failure (1 paper, 2020). The significant impairment of gas exchange within the lungs resulting in hypoxia, hypercarbia, or both, to the extent that organ tissue perfusion is severely compromised. "Elevated protein chaperones Hspa1a and Hspa1b in medulla during SA may reflect a seasonal remodeling of electrophysiological properties to protect against respiratory failure at low temperatures, as shown for hamsters prior to hibernation." (PMID 33536943, 2020).
retinal degeneration (1 paper, 2023). Degeneration of the retina. "In certain models of retinal degeneration, HSPA1A overexpression is thought to play a protective role in stressed photoreceptors." (PMID 37371046, 2023).
sarcoma (1 paper, 2008). A usually aggressive malignant neoplasm of the soft tissue or bone. "Upregulation of HSPA1A significantly increased chemosensitivity of HT1080 to mitomycin C.The apoptogenic effects of taxanes on sarcoma could be increased by co-therapy with stimulators of HSPA1A expression." (PMID 19077262, 2008). "Furthermore, the apoptogenic effects of taxanes on sarcoma could be increased by co-therapy with STA-4783, a stimulator of HSPA1A expression." (PMID 19077262, 2008).
SARS-CoV infection (1 paper, 2021). "It is also noteworthy that HSPA1A and HSP90 are also significantly upregulated during SARS-CoV infection of Vero E6 cells." (PMID 34073047, 2021).
stomach adenocarcinoma (1 paper, 2021). "HSPA1A CNVs were correlated with shorter survival time in stomach adenocarcinoma (HR = 1.317, OR = 1.044–1.661, p = 0.02) and esophageal carcinoma (HR = 1.386, OR = 1.007–1.908, p = 0.045)." (PMID 34712697, 2021).
thyroid cancer (1 paper, 2024). "Most of the genes showed the same trend as transcriptomics, and in particular, CD177, HSPA1A, HSP1B, and S100A12 were significantly increased in advanced thyroid cancer compared to in indolent thyroid cancer." (PMID 38719807, 2024).
triple-negative breast carcinoma (1 paper, 2021). An invasive breast carcinoma which is negative for expression of estrogen receptor (ER), progesterone receptor (PR), and human epidermal growth factor receptor 2 (HER2). "HSPA1A knockdown by siRNA in triple negative breast cancer-derived MDA-MB-231 cells abrogated their resistance to radiation exposure; this suggests a possibility of targeting the HSP70 expression to improve the action of radiotherapy against triple negative breast cancer." (PMID 34943954, 2021).
tumor (100 papers, 2010 to 2026). "The human genome contains nine Hsp70-family genes; HSPA1A encodes Heat shock 70 kDa protein 1A (HSPA1A/Hsp70-1), the expression of which is upregulated in diverse types of tumor cells." (PMID 37240404, 2023). "Elevated HSPA1A levels were associated with advanced histological tumor grade (p < 0.001) and with the cell proliferation index (KI67) (p = 0.0418)." (PMID 35906272, 2022). "Expression of the Heat shock 70 kDa protein 1 (HSPA1A) gene is inducible and was associated with poor prognosis in an extensive number of cancers, while involved in tumor growth, invasion, migration and resistance to anti-cancer therapy." (PMID 35414137, 2022). "Together, our findings establish ARID2 as an important tumor suppressor in LUADs with novel mechanistic insights, and further identify HSPA1A as a potential therapeutic target in ARID2-deficient LUADs." (PMID 34858604, 2021). "HSPA1A associated with exosomes was shown to reduce tumor immune surveillance by promoting activation of myeloid-derived suppressor cells." (PMID 28468249, 2017). "Therefore, it is possible that the decreased expression of HSPA1A represents a protective mechanism initiated by the body to cope with the continuous genetic and cellular changes associated with tumor formation." (PMID 37993485, 2023). "Notably, we found that the direction of activation and differentiation of infiltrating T cells in HER2 + IBC tumours was associated mainly with the NF-KB signalling pathway, which is characterized by high expression of heat shock protein-related molecules (HSPA1A, HSPA1B)." (PMID 40624675, 2025). "JUN, FOS, STAT3, JUND and NR2F1 were up-regulated in clusters C2 and C3, leading to tumor progression and immune evasion by influencing target genes HSPA1A, CXCL9 and PDGFR." (PMID 42074110, 2026). "Evidence revealed that HSPA1A promotes tumor cell proliferation and invasion, contributing to the progression and recurrence of GBM." (PMID 40777122, 2025). "The expression of heat-shock protein-related genes such as HSPA6,HSPA1B, and HSPA1A equips this macrophage subset to cope with the stressful tumor microenvironment and play a role in immune regulation." (PMID 41394809, 2025). "Overexpression of HSPA1A significantly enhances cell proliferation, with cellular immunofluorescence revealing its primary localization in the cytoplasm, where it promotes tumor cell proliferation." (PMID 40777122, 2025). "Prolonged exposure to HSPA1A can lead to the development of immune tolerance, which promotes tumor growth." (PMID 41369326, 2025). "Collectively, our findings at the single-cell level strongly implicate IKBKE and HSPA1A in the regulation of local immune responses and the modulation of the tumor microenvironment in LIHC." (PMID 39000042, 2024). "Induction of apoptosis (p < 0.05) coincided with suppression of Bcl2 and Hspa1a, and suppression of tumor angiogenesis coincided with suppression of F7, Fak3 and Frzb (involved in the regulation of growth and differentiation of certain cell types)." (PMID 35330327, 2022). "We analyzed the mRNA expression levels of Hsp70 (HSPA1A) in normal and tumoral breast tissues using two published databases, the Gene Expression database of Normal and Tumor tissues (GENT2) and Gene Expression Profiling Interactive Analysis (GEPIA)." (PMID 36230821, 2022). "Intracellular HSPA1A protected tumor cells from immune attack in both in vitro and in vivo experiments." (PMID 35887137, 2022). "HSPA1A (heat shock protein family A member 1A) can stabilize existing proteins and mediate the correct folding of proteins in the cytoplasm and organelles, thereby protecting tumor cells and enhancing their recovery." (PMID 35600868, 2022). "Some studies have shown that HSPA1A can enhance the apoptosis resistance of H22 cells to promote tumor growth by activating NF- κB, and HSPA1A of extracellular to the endogenous ligand of TLR4 and TLR2." (PMID 34059060, 2021).